EWSR1 (EWS RNA binding protein 1)
Diseases named in the same sentence as EWSR1 in open-access papers (continued):
Sharing a sentence is not in itself a finding about the gene and the disease.
prostate carcinoma (17 papers, 2011 to 2024). A carcinoma that arises from epithelial cells of the prostate gland. "In prostate cancer, we found that AR drives formation of a shortened EWSR1 isoform that promotes cancer-associated phenotypes." (PMID 34409300, 2021). "Ewing sarcoma breakpoint region 1 (EWSR1) encodes a multifunctional protein that can cooperate with the transcription factor ERG to promote prostate cancer." (PMID 34409300, 2021). "Androgen regulates EWSR1 breakpoint formation by inducing R-loop accumulation for DNA damage in prostate cancer." (PMID 36923313, 2022). "We previously found that EWS plays an important role in prostate cancer, therefore we investigated the relationship between EWSR1 expression and AR expression, as AR is essential for prostate cancer development and progression." (PMID 34409300, 2021). "We have shown in the prostate cancer setting that AR binds to intron 5 of EWSR1 to directly upregulate a previously uncharacterized isoform that we have termed ntEWS." (PMID 34409300, 2021). "Here we find that in prostate cancer, androgen signaling upregulates a 5′ EWSR1 isoform by promoting usage of an intronic polyadenylation site." (PMID 34409300, 2021). "This may be due to different chromatin states between DSRCT and prostate cancer cells, or could suggest a model in which AR binds to EWSR1::WT1, resulting in AR recruitment to WT1 binding sites." (PMID 38575753, 2024). "While it is known that AR promotes gene fusion formation in prostate cancer, an androgen-dependent mechanism for EWSR1 breakage has not been shown." (PMID 34409300, 2021). "Although we were able to generate EWSR1 breakpoints at high frequencies in a prostate cancer cell line, EWSR1 rearrangements are not common in prostate cancer." (PMID 34409300, 2021).
soft tissue sarcoma (16 papers, 2012 to 2025). A malignant neoplasm arising from muscle tissue, adipose tissue, blood vessels, fibrous tissue, or other supportive tissues excluding the bones. "These cases demonstrate the potential of Pazopanib as a promising therapeutic option for patients with EWSR1::CREM fusion-positive soft tissue sarcomas, including metastatic undifferentiated round cell sarcomas." (PMID 37829338, 2023). "Soft tissue sarcomas harboring EWSR1::CREM fusion are rare and challenging to treat." (PMID 37829338, 2023). "Preclinical experiments suggest that PARP inhibitor treatment can potentiate the effect of chemotherapy or radiotherapy in soft tissue sarcomas, particularly with gene fusions EWSR1::FLI1 and EWSR1::ERG." (PMID 40134582, 2025). "The EWSR1::NFATC2 bone and soft tissue sarcomas presented as slowly growing masses." (PMID 36555836, 2022). "A distinct entity is formed by PLAGL1 rearranged EPNs, harboring EWSR1–PLAGL1 and less commonly PLAGL1–FOXO1 or PLAGL1–EP300 fusions, which echoes molecular landscapes of soft tissue sarcomas and a group of rare mesenchymal (non-meningothelial) and glioneuronal CNS tumors with EWSR1–non-ETS fusions." (PMID 34638438, 2021).
clear cell carcinoma (15 papers, 2013 to 2025). "Hyalinizing clear cell carcinoma (HCCC) is a carcinoma composed of clear and eosinophilic cells in a variably hyalinized stroma, usually associated with EWSR1 rearrangement." (PMID 38217715, 2024). "EWSR1 gene rearrangements are present in hyalinizing clear cell carcinomas, similar to hyalinizing clear cell carcinomas in the head and neck and lung." (PMID 38067300, 2023). "Hyalinizing clear cell carcinomas (HCCC) with EWSR1 rearrangement can occur in the thymus and have been included in the 2021 WHO classification." (PMID 38067300, 2023). "For the head and neck region, mucoepidermoid carcinoma, clear cell carcinoma and myoepithelial carcinoma have been reported to have EWSR1 gene rearrangement." (PMID 33715971, 2022). "These include fusions of the ETV6 gene in secretory carcinoma (SC), MYB/MYBL1::NFIB in adenoid cystic carcinoma (AdCC), CRTC1/CRTC3::MAML2 in mucoepidermoid carcinoma (MEC), and EWSR1::ATF1 in hyalinizing clear cell carcinoma as the most frequent and best characterized gene fusions." (PMID 38217715, 2024). "In hyalinizing clear cell carcinoma, ATF1 could fuse with EWSR1 and was associated with tumor development." (PMID 35568813, 2022). "The demonstration of EWSR1 translocations in a subset of CCOCs establishes a molecular link with hyalinizing clear cell carcinoma (HCCC) of the salivary glands, which is also characterized by EWSR1 rearrangements." (PMID 41364259, 2025). "80% of these carcinomas also show rearrangements in the EWSR1-ATF genes, although these rearrangements also appear in salivary gland hyalinizing clear cell carcinoma and other clear cell neoplasms." (PMID 32388513, 2020). "A subset of fusion‐negative salivary gland MECs were found to host (EWS RNA binding protein 1) EWSR1 mutations, and it has been proposed to reclassify these tumors as hyalinizing clear cell carcinoma, which has a relatively better prognosis." (PMID 36916425, 2023). "For primary thymic HCCC the 2021 WHO classification indicates that clear cell carcinomas without EWSR1 rearrangement may or may not represent true thymic clear cell carcinoma." (PMID 38067300, 2023).
glioma (15 papers, 2017 to 2025). A benign or malignant brain and spinal cord tumor that arises from glial cells (astrocytes, oligodendrocytes, ependymal cells). "Its mutational analysis identified previously identified hereditary gene changes such as MSH6 known to confer susceptibility to glioma, BRCA1 germline mutation which is extremely rare in gliomas, as well as a novel mutation EWSR1 in glioma." (PMID 35370679, 2022). "Emerging studies have revealed that circNEIL3 contributes to angiogenesis in glioma tissues, a process promoted by EWSR1, whose activity is elevated under hypoxic conditions." (PMID 40723354, 2025). "EWS RNA-binding protein 1 (EWSR1) increases the circularization of circNEIL3, leading to its upregulation and subsequent glioma progression." (PMID 40723354, 2025). "For the RBPs mechanism, it has been shown that EWS RNA-binding protein 1 (EWSR1) promotes circNEIL3 biogenesis in gliomas." (PMID 38544689, 2024). "In these rare gliomas, EWSR1 represents an alternate fusion partner, which however became more frequently encountered than the originally described MN1::BEND2 fusion." (PMID 36690805, 2023). "Accumulating evidence suggests that EWSR1-induced circNEIL3/IGF2BP3 enhances glioma progression by regulating macrophage polarization and circRNA-0002109 enhances glioma malignant progresses by regulating the miR-129-5P/EMP2 axis." (PMID 37540226, 2023). "We found that the EWSR1 expression level increased with the grade of glioma, and patients with high expression of EWSR1 had a worse prognosis than those with low expression." (PMID 35031058, 2022). "More recently, a comprehensive genomic profiling of pediatric gliomas identified a rearrangement of the PATZ1 gene (exons 1–5 of PATZ1 fused downstream to exons 1–9 of EWSR1) in a pediatric high-grade glioma." (PMID 29186807, 2017). "Interestingly, a single case of atypical central neurocytoma with EWSR1::ATF1 fusion and MUTYH G382D mutation (detected via NGS) achieved ~3 years of PFS with conventional glioma therapy in a 13-year-old patient." (PMID 40575153, 2025). "The expression of circNEIL3, which could be regulated by EWSR1, increased with the increasing glioma grade." (PMID 35031058, 2022). "EWSR1 promotes glioma progression by cyclizing circNEIL3, thereby blocking HECTD4-mediated ubiquitination, stabilizing IGF2BP3, and promoting glioma progression." (PMID 37964279, 2023). "In decreasing order of frequency, EWSR1, MN1, and MAMLD1 are the reported fusion partners of BEND2 in astroblastoma-like gliomas." (PMID 36690805, 2023). "The expression of circNEIL3, which can be regulated by EWS RNA-binding protein 1 (EWSR1), increased with the increasing grade of gliomas." (PMID 35031058, 2022). "In contrast to these findings, overexpression of PLAGL1 was found to contribute to the tumorigenesis of glioma-initiating cells and recurrent PLAGL1 fusions (most commonly with EWSR1) were found to characterize a novel subtype of supratentorial ependymoma-like tumor in pediatric patients." (PMID 36437415, 2023). "We identified circNEIL3, which could be cyclized by EWS RNA-binding protein 1(EWSR1), to be upregulated in glioma tissues and to correlate positively with glioma malignant progression." (PMID 35031058, 2022).
metastatic disease (15 papers, 2017 to 2024). "Sanger sequencing of the PCR products further validated the precise joining of EWSR1 exon 7 to WT1 exon 8 in RNA transcripts from both the primary and metastatic tumor samples." (PMID 37457440, 2023).
extraskeletal myxoid chondrosarcoma (14 papers, 2010 to 2025). A rare malignant soft tissue neoplasm of uncertain differentiation, characterized by the presence of chondroblast-like cells in a myxoid stroma and a multinodular growth pattern. "Additional FISH assays for WT1, CHN and DDIT3 (3' partners of EWSR1 in desmoplastic round cell tumor, extraskeletal myxoid chondrosarcoma and round cell liposarcoma, respectively) were negative." (PMID 20598147, 2010). "EWSR1‐CREB‐family fusion shows a myxoid component, which was previously diagnosed as consistent with extraskeletal myxoid chondrosarcoma (EMC)." (PMID 33713576, 2021).
Ewing family tumors (13 papers, 2008 to 2023). "As DSRCTs harbor EWSR1-related translocations, they could be examined in clinical trials that target EWSR1 or its surrounding signaling molecules along with other Ewing-family tumors." (PMID 30487384, 2018). "Recently, in addition to Ewing family tumors, round cell sarcomas with EWSR1 gene fusion, BCOR-rearrangement, and CIC-rearrangement have been recognized as new entities; furthermore FISH and PCR are essential for the differential diagnosis between ES and Ewing family tumors." (PMID 36686838, 2022).
myoepithelial carcinoma (12 papers, 2012 to 2025). "HRAS exon three mutations and a high percentage of EWSR1 rearrangements are commonly detected in clear cell subtype myoepithelial carcinoma." (PMID 39958930, 2025). "Cases of SMARCB1-deficient tumors, such as extrarenal rhabdoid tumors and myoepithelial carcinomas, harboring concurrent EWSR1 gene abnormalities, which resulted in misinterpretation of EWSR1 gene FISH results, have been reported." (PMID 40366517, 2025). "Previously, SMARCB1-deficient myoepithelial carcinoma of soft tissue was reported to have an EWSR1 gene rearrangement located on the same chromosome 22 as SMARCB1 without SMARCB1 gene abnormalities." (PMID 38836164, 2024). "In fact, one of the tumors of the current series was initially diagnosed as a myoepithelial carcinoma due to the expression of cytokeratins and the presence of the EWSR1 rearrangement." (PMID 31049020, 2019).
acute lymphoblastic leukemia (11 papers, 2013 to 2025). Leukemia with an acute onset, characterized by the presence of lymphoblasts in the bone marrow and the peripheral blood. "The FLI1::EWSR1 gene fusion is a rare and atypical event in acute lymphoblastic leukemia (ALL), not typically classified among the canonical translocations driving the disease." (PMID 41228238, 2025). "Critically, recurrent chromosomal translocations involving the ZNF384 gene, which result in fusion proteins with partners such as EWSR1, TAF15, and EP300, are frequently observed in the pathogenesis of acute lymphoblastic leukemia (ALL)." (PMID 41429980, 2025).
chondrosarcoma (11 papers, 2011 to 2026). A malignant cartilaginous matrix-producing mesenchymal neoplasm arising from the bone and soft tissue. "The same holds true for rearrangements involving NR4A3 in extraskeletal myxoid chondrosarcomas: while the AMP-FPS assay covers the most NR4A3 common partners (EWSR1, TAF15, TCF12, TFG) it lacks probes for both NR4A3 and uncommon partners, thus scoring negative in the presence of alternative fusions." (PMID 32351889, 2020). "In two cases, one SEF and one mesenchymal chondrosarcoma, RNA quality was insufficient for fusion gene analysis, although in the SEF, EWSR1 rearrangement using FISH and MUC4 positivity confirmed the diagnosis." (PMID 38332052, 2024).
breast carcinoma (9 papers, 2013 to 2025). "Here, we first described that RNF114 promotes tumor proliferation and autophagy by interacting with EWSR1 and regulating VEGFR2 expression in HER2-positive breast cancer (BC)." (PMID 40092691, 2025). "This was further validated using three different shRNA constructs to knockdown the human homologue, EWSR1, in MCF7 breast cancer cells (20-fold lower SF50, P<0.001, ANOVA), suggesting that EWSR1 might be a genetic determinant of PARP inhibitor sensitivity." (PMID 28248920, 2017). "The tumor suppressor let-7a is, for example, known to be directly downregulated by EWSR1–ETS, but this decrease in let-7a does not lead to increased CCR7 expression like in breast cancer cells." (PMID 27369431, 2016).
frontotemporal dementia (9 papers, 2012 to 2022). Frontotemporal dementia (FTD) comprises a group of neurodegenerative disorders, characterized by progressive changes in behavior, executive dysfunction and language impairment, as a result of degeneration of the medial prefrontal and frontoinsular cortices. "For instance, recent evidence has linked EWSR1, another RBP very similar to FUS and TAF15, to frontotemporal lobar degeneration with ubiquitin-positive inclusions (FTLD-U)." (PMID 22919483, 2012). "Potentiated Hsp104 variants also rescue toxicity and aggregation of TAF15 but not EWSR1, two RNA-binding proteins with a prion-like domain that are connected with the development of ALS and frontotemporal dementia." (PMID 25062688, 2014).
myxoid chondrosarcoma (9 papers, 2011 to 2024). A chondrosarcoma characterized by the presence of myxoid changes. "Translocations that fuse the NR4A3 and EWSR1 genes occur in a majority of extraskeletal myxoid chondrosarcomas, and the resulting EWSR1-NR4A3 fusion protein is thought to be the driver oncogene for most such tumors." (PMID 32867110, 2020). "The EWSR1 (EWS RNA binding protein 1)/NR4A3 fusion protein of extraskeletal myxoid chondrosarcoma activates PPARγ which is crucial for lipid metabolism regulation." (PMID 28800357, 2017).
brain tumor (7 papers, 2017 to 2025). "NEpTs harboring EWSR1::PATZ1 fusions represent an exceptionally rare subgroup of primary brain neoplasms, currently unrecognized by the WHO classification system." (PMID 40575153, 2025). "Recent reports have identified a handful of pediatric brain tumors displaying a fusion of the PATZ1 gene with either MN1 or EWSR1 as a partner." (PMID 35204463, 2022). "To determine whether EWSR1 cytoplasmic aggregates were also present in GBM clinical specimens, we stained a cohort of 21 brain tumor samples, including 15 GBMs, for EWSR1." (PMID 35731869, 2022). "For EWSR1-CREM, EWSR1-PLAGL1 and EWSR1-PATZ1 tumors, no significant methylation scores were reached in the known brain tumor classes." (PMID 32997853, 2020).
mesothelioma (7 papers, 2021 to 2026). A usually malignant and aggressive neoplasm of the mesothelium which is often associated with exposure to asbestos. "The other mesotheliomas and EWSR1::YY1-rearranged lesions were more distant from the AFH cluster." (PMID 39059063, 2024). "Whether or not AFH (including its myxoid variant), PPMS, so-called mesothelioma, and EWSR1-CREM undifferentiated sarcoma are a spectrum of one tumor type will yield further studies in the future." (PMID 34203801, 2021). "Among the non-mesenchymal categories, EWSR1::ATF1 fusions define the majority of hyalinizing clear cell carcinoma of head and neck and have been reported also in a rare subset of mesotheliomas." (PMID 39031200, 2024).
mucoepidermoid carcinoma (7 papers, 2010 to 2024). A carcinoma morphologically characterized the presence of cuboidal mucous cells, goblet-like mucous cells, squamoid cells, cystic changes, and a fibrotic stromal formation. "With the expression pattern of CREM portrayed, we also test whether CREM IHC could be used as an indicator of the presence of EWSR1-CREM fusion gene in low-grade mucoepidermoid carcinoma (MEC)." (PMID 34261344, 2021).
acute myeloid leukemia (6 papers, 2015 to 2025). Acute myeloid leukemia (AML) is a group of neoplasms arising from precursor cells committed to the myeloid cell-line differentiation. "They demonstrated that many recurrent chromosomal translocations, of PML/RARα observed in Acute Promyelocytic Leukemia (APL), MLL/AF9 in Acute Myeloid Leukemia (AML), EWSR1/FLI1 in Ewing Sarcoma and EML4/ALK1 associated with lung cancer could form f-circRNAs." (PMID 30018188, 2018). "In addition, chromosomal translocations between the EWSR1 and FLI1 loci and between the AML1 (also known as RUNX1) and ETO (also known as RUNX1T1) loci, which are involved in Ewing’s sarcoma and acute myeloid leukemia (AML), respectively, have been generated by CRISPR in human cell lines." (PMID 26060510, 2015).
bone sarcoma (6 papers, 2014 to 2023). A sarcoma that arises from the bone. "Furthermore, STS had a higher mutation frequency of EWSR1 fusions than bone sarcomas (p < 0.01)." (PMID 37546405, 2023). "In this case report, we discuss the case of a patient with a EWSR1-NFATC2 fusion positive bone sarcoma who had exceptional tumor control through using pazopanib and surgery for an overall duration exceeding 5 years." (PMID 37736255, 2023).
Wilms tumor (6 papers, 2012 to 2021). An embryonal neoplasm characterized by the presence of epithelial, mesenchymal, and blastema components. "However, WT1 was negative and EWSR1 gene was identified by FISH, and therefore adult Wilms' tumor was ruled out." (PMID 22312368, 2012).
medulloblastoma (5 papers, 2015 to 2026). A malignant, invasive embryonal neoplasm arising from the cerebellum. "Nine of the 15 GBM samples were positive for EWSR1 cytoplasmic amyloid–like aggregates (cohort 1), while none of the anaplastic astrocytomas or medulloblastomas showed this staining pattern." (PMID 35731869, 2022).
mesenchymal chondrosarcoma (5 papers, 2011 to 2025). A morphologic variant of chondrosarcoma arising from bone and soft tissue. "On further immunohistochemistry with NKX3.1 and EWSR1 break-apart fluorescent in situ hybridization analysis, a diagnosis of mesenchymal chondrosarcoma was rendered which was later on confirmed with biphasic histology on excision specimen." (PMID 40323235, 2025). "Interestingly, mesenchymal chondrosarcoma and round cell sarcomas with EWSR1-NFATC2 fusions have been recently found to express the related protein, NKX3.1, more widely known as a marker of prostatic differentiation." (PMID 33921435, 2021).